AR (androgen receptor)
Diseases named in the same sentence as AR in open-access papers (continued):
Sharing a sentence is not in itself a finding about the gene and the disease.
prostate tumors (continued). "Castration resistant prostate tumors are frequently characterized by increased expression of full-length AR (ARFL), and as recently reported, by increased expression of ARsv that lack the LBD and consequently confer constitutive ligand-independent AR activity." (PMID 25356728, 2014). "Castration of PtenLoxP/LoxP:Osr1-Cre mice shows no significant regression of prostate tumors, although a shift of androgen receptor (AR) staining from the nuclei to cytoplasm is observed in Pten null tumor cells of castrated mice." (PMID 23308230, 2013). "We then sought to determine whether BA can decrease the expression levels of AR and cyclin D1 proteins in TRAMP prostate tumors." (PMID 23424652, 2013). "Castration of PtenLoxP/LoxP:Osr1-Cre mice shows no significant regression of prostate tumors, although a shift of AR staining from the nuclei to cytoplasm is observed." (PMID 23308230, 2013). "Unlike the results in prostate tumors, the levels of AR in normal prostate were similar in BA10 compared to vehicle control, suggesting that the BA-mediated degradation of AR occurred only in tumor cells." (PMID 23424652, 2013). "The therapeutic effects of VK2 may, therefore, also be partly explained by reductions in both androgen receptor expression and AKT activation in LNCaP and 22RV1 derived prostate tumors." (PMID 24062781, 2013). "The present and several previous studies evaluated germline AR-CAG repeat lengths in peripheral blood samples, but the actual repeat lengths within the prostate tumors might play a more critical role in response to ADT." (PMID 23359804, 2013). "Together, these data show that ganetespib treatment can significantly inhibit prostate tumor growth, again irrespective of androgen receptor status." (PMID 23152004, 2013). "Of the 218 prostate tumors, 34.4% had reduced expression of STRADA, 18.3% exhibited overexpression of TTK, 11.7% either overexpressed or had reduced expression of AKT1, and 15.6% of tumors overexpressed or had amplified AR." (PMID 22509301, 2012). "Unlike AR, STRADA, TTK, and AKT1 showed little evidence of gene amplification or loss in human prostate tumors." (PMID 22509301, 2012). "As a readout for the screen, we used a reporter construct containing the cis-regulatory promoter region (5.8 kb containing an AR enhancer) of the prostate-specific antigen (PSA) gene, which is highly expressed in the normal prostate epithelium and in prostate tumors." (PMID 21267413, 2011). "Coupling up-regulated AR with the fact that testosterone and DHT concentrations were higher in SV-40 Tag rats makes a strong case for increased cell proliferation in the prostate and of prostate tumor development in this animal model." (PMID 19171036, 2009). "Since PC-3 cells are known to be AR-negative and clinically most prostate tumours express the AR, it was important to determine if the effects of the combination treatment were independent of AR status." (PMID 18349838, 2008). "Similar to that observed in ERα-positive MCF-7 breast tumour cells, RES inhibited DNA synthesis and modulated cell cycle progression in androgen receptor (AR)-positive LNCaP but not in AR-negative DU145 human prostate tumour cells." (PMID 17486135, 2007). "Of note, DU145 and PC3 cell lines, which no longer express AR, are representative of a proportion of advanced prostate tumors where AR is no longer required for tumor growth." (PMID 17925854, 2007). "However, by using AR transcriptional activity as a surrogate marker of RCB, we found that AR activity and HER2 activity remain as distinctly inverse properties of prostate tumors that could be extended to other case sets." (PMID 40906535, 2025). "Therefore, we investigated the AR, FOXA1, and HOXB13 binding in the regulatory regions (−15 kb/+2 kb from TSS) of the DEGs by utilizing previously published prostate tumor and prostate normal tissue-specific AR-binding sites (ARBSs) and FOXA1- and HOXB13-binding sites in PCa tumor samples." (PMID 40525903, 2025).
prostate tumors (continued). "To better understand the role that AR gene mutagenesis plays in prostate carcinogenesis, we conducted a massive, next-generation sequencing (NGS) analysis of a panel of genes highly relevant for PCa in prostate tumor biopsies from a scarcely studied cohort, namely Hispanic patients." (PMID 41009328, 2025). "Thus, because this subset of never-before-treated, de novo prostate tumors were showing little (or no) AR activity by transcriptional and histologic profiling, ADT would not be appropriate as a universal first-line systemic therapy." (PMID 40906535, 2025). "ADT in xenograft model increased bone metastasis of prostate tumors via repression of transcription factor SPDEF and induction of TGFB I.11These contradictory findings suggested that AR may have dual roles on PCa metastasis and the molecular mechanism lying underneath may be complicated." (PMID 39149855, 2024). "In the 4,490 prostate tumor biopsies, APUC-6 genes exhibited a robust correlation with one another, and all had strong positive correlations with ESR1, ESR2, and PGR (Spearman’s R 0.13–0.52), while the correlation with AR was relatively weak (Spearman’s R 0.06–0.20)." (PMID 39207857, 2024). "We speculate that during the treatment of ADT, the function of AR was inhibited, IL-6 and STAT3 were activated for compensation, and the expression of IL-6 and STAT3 promoted the increased synthesis of FGG, thereby promoting the growth of the prostate tumor." (PMID 33995485, 2021). "In support of our proposition, a reanalysis of AR binding with an AR ChIP-seq dataset containing both normal and tumor samples of prostate cancer revealed that AR binds only to the PVR enhancer region in the prostate tumor samples but not in the normal prostate tissue." (PMID 33343635, 2020). "However, it is increasingly accepted that AR‐negative subpopulations of PCa are present in prostate tumors such as neuroendocrine populations or stem‐cell‐like PCa cells." (PMID 31630475, 2020). "Interestingly, LNCaP and prostate tumors, but not the healthy tissues, exhibited AR and FOXA1 binding at this region, again confirming the specificity of the enhancer to prostate tumors." (PMID 32680982, 2020). "Interestingly, the vast majority of AR sites found in PCDFs, and induced by R1881, were unique for this cell type and not shared with those found in prostate tumors and the PCa cell line LNCaP." (PMID 29808619, 2018). "Thus, the results indicated that the high expression of CXCL13 was significantly correlated with prostate tumor in clinic, and the expression of CXCL13 might be up-regulated by androgen/AR axis." (PMID 28881808, 2017). "However, targeting androgen-dependent prostate cells does not eradicate the stem cell component of prostate tumours, which we and others have shown to have an AR-negative phenotype." (PMID 28915623, 2017). "Thus, besides the effects of USP7 inhibitors on the stability of AR isoforms and their transcriptional gene targets, we asked whether the treatment with USP7 inhibitor was also able to affect the CCDC6 stability in prostate tumor cells." (PMID 28415632, 2017). "Indeed, the aggressiveness of prostate tumor cells expressing the OR51E2 receptor could increase due to their exposure to ionones and independently of androgen stimulation of the androgen receptor or the OR51E2 receptor." (PMID 28032594, 2017). "Overall, these findings demonstrated that the process of translocating AR from the cytoplasm to the nucleus was unaffected by chemical or genetic disruptions in COPI-mediated retrograde protein trafficking and that the COPI complex regulated nuclear levels of ARA160 in LNCaP prostate tumor cells." (PMID 27365400, 2016). "We speculate that the discordant effects on AR-mediated transcription observed between the siRNA luciferase screen and reported AR coregulator functions of MDM2, RNF6, and USP10 in prostate tumor cells are due to differences in prostate tumor cell lines and reporter vectors." (PMID 27365400, 2016).
prostate tumors (continued). "However, cells transfected with validated MDM2 siRNAs failed to potentiate AR transcriptional activity in LNCaP prostate tumor cells." (PMID 27365400, 2016). "We also demonstrated a strong positive correlation between AR copy number gain and increased level of AR mRNA expression, supporting previous studies which showed higher levels of AR protein expression in prostate tumors with AR gene amplification than tumors without AR amplification." (PMID 24098661, 2013). "Furthermore, AR expression has been validated on CD34+ cells and with regards to more tissue specific stem cells, AR expression has been seen in putative stem cell population from prostate tumor lines." (PMID 24772452, 2013). "The reduced expression of AR in the prostate tumors of Pten-negative mice supports this idea." (PMID 24199173, 2013). "Therefore, the observed cross-talk between the AR and EGFR axes leads to the assumption that EGFR-induced EMT and androgen-independence could occur simultaneously in prostatic tumor cells." (PMID 23185449, 2012). "Transcripts for the normal ARfl and the most abundant AR splice variants known so far; AR-V1, AR-V7, and AR-V567es, were detected and their levels quantified in non-malignant and GS7-8 tissue parts of primary prostate tumors and in bone metastases samples, using real-time RT-PCR analysis." (PMID 21552559, 2011). "To the best of our knowledge, we are the first to determine that selenium consumption does not alter glutathione peroxidase activity in the prostate or prostate tumors.Selenium consumption did not alter androgen receptor, probasin, SBP2, Sep15, or SepP prostate or tumor mRNA expression." (PMID 20454690, 2010). "Having observed that in PCa cells, hSSB1 modulates the transcriptional response following DNA damage, and that AR signaling controls the expression of DDR genes impacting radiosensitivity, we sought to determine whether a correlation between hSSB1 and AR existed in prostate tumors." (PMID 36811381, 2023). "Likewise, in prostate tumour cells, direct methylation of KDM1A by the protein-methyltransferase EHMT2 facilitates an interaction between the chromatin remodeling proteins CHD-1 and KDM1A, that is necessary for androgen receptor dependent transcriptional activation." (PMID 33068438, 2020). "Second messenger signaling via the androgen receptor is indispensable for the prostate epithelial cells, not only for the normal functioning and homeostasis of the prostate gland but also for the development of prostatic neoplasms and the progression of PC to CRPC." (PMID 31940946, 2020). "Hence, our results evidently suggest that specific elimination of SPINK1 from the whole spectrum of SASP in the treatment-damaged TME increases tumour response to chemotherapy, a result independent of androgen response or AR signaling of prostate tumours per se." (PMID 30333494, 2018). "Thus peptide growth factors may function as alternative survival/growth pathways, for example in the subgroup of AR negative prostate tumors, and/or as an adaptation of AR pathway by preserving AR activity under androgen ablation conditions." (PMID 20976069, 2010). "AR gene amplification and copy number alterations are detected in up to 60% of metastatic CRPC patients but not in untreated primary prostate tumors." (PMID 35966880, 2022). "As seen in previous studies of TRAMP tumors, blood-derived TRAMP tumor cells in the liver lacked immunoreactivity for androgen receptor (AR) but stained strongly for SV40 T-Ag, consistent with primary TRAMP prostate tumors." (PMID 23530114, 2013). "Maspin expression is also lost with prostate tumor progression, through inactivation of a positive Ets response element and activation of a negative HRE response element recognized by AR." (PMID 22857708, 2012).
prostate tumors (continued). "Here, we demonstrate that LeY expression is detected in both adenocarcinoma and neuroendocrine prostate cancer, and is independent of AR or PSMA, and thus LeY CAR T cells could be applicable for the treatment of a diverse range of prostate tumors." (PMID 37660083, 2023). "Unlike the AR antagonists, enzalutamide is an enzymatic inhibitor for p450 17A1 (CYP17) capable of irreversibly blocking steroid conversion in the biosynthesis pathway of active androgens in prostatic tumor cells." (PMID 37025180, 2023). "Moreover, PRK1 can control the transcriptional activation of AR-target genes even in the absence of testicular androgens or in the presence of anti-androgens, highlighting a role for PRK1 in prostate tumour growth and spread which occurs during ADT and CRPC." (PMID 26296974, 2015). "The other major extrahepatic P450 isoform expressed in normal and prostate tumor is CYP1A1, bergamottin is a competitive inhibitor of CYP1A1 and can aid in cancer chemoprevension due to CYP1A1s role in carcinogenesis, this inhbitory effect is independent of bergamottins affect on CYP3A5 and AR." (PMID 34570813, 2021). "Indeed, the levels of PSMA expression in prostatic tumors, their related metastases and levels of serum PSA might not correlate with each other, as the expression of PSA, unlike PSMA, is mainly promoted by androgens and regulated by the androgen receptor." (PMID 34065303, 2021).
triple-negative breast carcinoma (216 papers, 2011 to 2026). An invasive breast carcinoma which is negative for expression of estrogen receptor (ER), progesterone receptor (PR), and human epidermal growth factor receptor 2 (HER2). "Tumors in older women with triple-negative breast cancer demonstrate less aggressive markers, such as androgen receptor positivity, which has been linked to lower recurrence rates and systemic therapy insensitivity." (PMID 40373794, 2025). "For example, apocrine differentiation is associated with androgen receptor expression which has been shown to result in better prognosis in triple-negative breast carcinoma." (PMID 33923191, 2021). "Previous studies have shown androgen receptor (AR) is associated with the occurrence, development, recurrence, metastasis, and prognosis of triple negative breast cancer (TNBC)." (PMID 32332626, 2020). "Several studies have confirmed that the positive expression of AR is significantly associated with poor survival, and increased mortality in AR-positive triple negative breast cancer (TNBC)." (PMID 29699584, 2018). "Our previous study showed that androgen receptor (AR) promotes triple-negative breast cancer (TNBC) cell tumorigenesis, but the underlying mechanisms remain unclear." (PMID 40118451, 2025). "Additionally, AR expression has been associated with predicting responses to neoadjuvant chemotherapy in triple-negative breast cancer (TNBC)." (PMID 40860264, 2024). "On the other hand, the correlation of ALCAM expression with AR gene expression score seems to be in line with current observations made in triple negative breast cancer where high ALCAM tissue protein expressions were shown to be associated with higher AR protein expression." (PMID 35689436, 2022). "Basal triple negative breast carcinomas showed an association with AR negativity." (PMID 32928183, 2020). "Previous study by Asghar U indicated that a subset of triple-negative breast cancer cells with expression of AR and the loss of cyclin E1 could be responsive to CDK4/6 inhibition." (PMID 28438180, 2017). "In addition, loss of AR in triple-negative breast cancers is associated with a worse prognosis, including those with basal-like features." (PMID 26862856, 2016). "The role of androgen receptors in triple-negative breast cancer is particularly relevant because androgen receptor–positive triple-negative breast cancer is associated with reduced sensitivity to conventional systemic therapies but may respond to antiandrogenic treatments." (PMID 40373794, 2025). "However, the role of ERβ1 in the metastasis of androgen receptor (AR)-positive triple-negative breast cancer (TNBC) and the underlying mechanisms are still unknown." (PMID 28583190, 2017). "In this context, the androgen receptor (AR) has emerged as a promising therapeutic target, particularly within the challenging subgroup of triple-negative breast cancers (TNBCs) that express it." (PMID 41590361, 2026). "Older women with triple-negative breast cancer exhibited less aggressive features, including lower Ki67, higher androgen receptor, and higher Bcl2 expression." (PMID 40373794, 2025). "Previous studies have also reported antiproliferative and antimetastatic effects of luteolin against androgen receptor (AR)-positive triple-negative breast cancer (TNBC) cell lines." (PMID 41304905, 2025). "AR positivity was highest in Luminal A/B subtypes (82%) and lowest in triple-negative breast cancer (TNBC) (20%; OR = 0.06, 95% CI: 0.01–0.3)." (PMID 40734715, 2025).